GUSBP1 (GUSB pseudogene 1)
Gene: Transcribed unprocessed pseudogene on chromosome 5 (21,459,560 to 21,501,826, forward strand). Ensembl gene ENSG00000183666.
Diseases named in the same sentence as GUSBP1 in open-access papers:
GUSBP1 is named in the same sentence as 4 diseases in open-access papers, as found by Europe PMC text mining. Sharing a sentence is not in itself a finding about the gene and the disease. The quoted sentences say what the papers report.
cancer (1 paper, 2020). A tumor composed of atypical neoplastic, often pleomorphic cells that invade other tissues. "DEF8, NDUFC2, GUSBP1, ARIH2, STX12 and HIST1H2BN were highly re-expressed (more than 100 folds) in either treatment of MV4-11, have not been previously discussed on their role in cancer except for HIST1H2BN." (PMID 32337016, 2020).
tumor (1 paper, 2017). "Only two genes were mutated in both of the aggressive human tumors but not in the curable PCB429 tumor; FAM86C1 and GUSBP1 contained either low- or modifier- impact mutations." (PMID 29100308, 2017).
GUSBP1 also shares sentences with these, for which no sentence is quoted: anemia (1 paper); colorectal cancer (1).